EGFR (epidermal growth factor receptor)
Diseases named in the same sentence as EGFR in open-access papers (continued):
Sharing a sentence is not in itself a finding about the gene and the disease.
tumor (continued). "Multiple mechanisms are engaged in the activation of the EGFR pathway during tumor initiation and progression, including receptor amplification and activation of receptor mutations." (PMID 32328181, 2020). "In detail, we evaluated the expression and localization of EGFR by IHC analysis on FFPE tumor samples derived from mice sacrificed at the end of treatment (day 21)." (PMID 33015030, 2020). "The bivalent α-EGFR-EGFR TM has shown to redirect UniCAR T cells to tumor cells expressing low levels of EGFR." (PMID 33101285, 2020). "There is irrefutable clinical evidence that primary tumor location serves as independent prognostic as well as predictive biomarker of response to anti-EGFR monoclonal antibodies in first line mCRC treatment." (PMID 32612957, 2020). "Our data extend the understanding of the Formo-mediated anti-tumor mechanism and suggest that suppression of both EGFR signaling and downstream oncoprotein is an alternative strategy to enhance the efficacy of the anti-tumor agent." (PMID 32276600, 2020). "Taken together, these findings suggest that the location of tumours on the left side can help predict the efficacy of anti-EGFR antibodies in mCRC patients with KRAS wt status." (PMID 33188279, 2020). "For EGFR, there was intense membranous staining of tumor cells, and a rare tumor also stained weakly in the tumor stroma cell population and subcutaneous tissue." (PMID 32516897, 2020). "The results showed that once-daily dosing of deguelin significantly inhibited the tumor growth in EGFR-activating mutant-harbored cells, including HCC827, H3255, and H1975 xenograft tumors." (PMID 32081857, 2020). "Combining amuvatinib and the epidermal growth factor receptor (EGFR) inhibitor erlotinib has also been shown to significantly inhibit tumor growth in PTEN-null LNCaP xenografts, accompanied by reduced AKT phosphorylation at S473 and T308." (PMID 33105713, 2020). "Correlations between the radiotracer uptake vs. changes in tumor growth and EGFR expression from immunoblots were analyzed." (PMID 32295603, 2020). "We further showed that the EGF/EGFR axis was critical for proliferation of tumor cells, as TAMs provided EGF to induce EGFR-positive OC cell proliferation." (PMID 32286255, 2020). "RCP physically links EGFR with β1 integrin and plays an important role in transporting α5β1 integrin- and EGFR- positive REs to the PM to promote invasion of tumour cells into fibronectin-rich 3D microenvironments." (PMID 32842549, 2020). "The epidermal growth factor receptor (EGF-R) remains one of the best-established targets for anti-tumor therapies." (PMID 31988343, 2020). "Human MSCs loaded with iron oxide-NPs showed an overexpression of epidermal growth factor receptor (EGFR) that resulted in an improved migration of the MSCs towards hypoxic area of the tumor." (PMID 32046010, 2020). "For that, we developed nanobodies targeting mouse VEGFR2, which is mainly overexpressed on tumor vasculature, and we combined these with an EGFR targeted nanobody." (PMID 32977602, 2020). "Dysregulation of EGFR has also been shown to occur as a result of a high level of expression of EGFR in normal epithelium cells which is close to tumor." (PMID 33273921, 2020). "Somatic mutations of EGFR and KRAS are characteristic mutations in lung AC-s that promote accelerated tumor growth and also affect drug response." (PMID 32434541, 2020). "HLA-I expression on tumor cells can be restored by nimotuzumab, reversing an EGFR-mediated mechanism of immune-escape of tumors." (PMID 32793499, 2020). "In order to investigate the mechanism of action involved in the effect produced by the combinations, we analyzed the expression of ABCG2 and EGFR in tumor cells." (PMID 32911509, 2020). "Serial sections of the tumor specimens were stained with hematoxylin and eosin (H&E) and antibodies to measure the expression of Ki67, EGFR, and PTPN12." (PMID 33050232, 2020).
tumor (continued). "Experimental studies on tumor-cell intrinsic STAT3 signaling mechanisms (particularly in the context of EGFR-driven NSCLC) further consolidated the notion of STAT3 as an oncogene in this disease." (PMID 32365499, 2020). "Immunofluorescence staining of surgical tumor resections from CRC patients showed EGFR co-localized with αSMA, a marker used to identify CAFs, suggesting that CAFs do express EGFR." (PMID 32481658, 2020). "MDSCs were found to promote the expression of PD-L1 in tumor cells in an epidermal growth factor receptor (EGFR)/mitogen-activated protein kinase (MAPK)-dependent manner." (PMID 33198059, 2020). "It has been reported that a combination of high expression in CK5/6 and EGFR in addition to expression of Ki-67, cT (tumor stage), and cN for stratification has great clinical significance." (PMID 33552956, 2020). "In NSCLC, the overexpression of the EGFR and HER2 proto-oncogenes is closely associated with tumor progression, treatment resistance, invasion, and metastasis." (PMID 32143669, 2020). "Aberrant c-MET activity can contribute to acquired tumor cell resistance to treatment with epidermal growth factor receptor (EGFR) targeting tyrosine kinases (TKIs) such as erlotinib." (PMID 32117721, 2020). "Among the EMT genes upregulated by EGFR blockade are a few collagenases, most probably related to providing tumour cells ability to invade the extracellular matrix." (PMID 32362655, 2020). "Tumor heterogeneity with concurrent patchy SCLC transformation and T790M EGFR resistance mutation in the same patients have been described." (PMID 35582610, 2020). "ROC analysis of the tumour content ratio from a biopsy-mounted slide was used to predict EGFR identification confirmed by cobas and showed the area under the curve (AUC) was 0.68 with a cut-off reference value of 9% (sensitivity 0.87, specificity 0.47)." (PMID 32028905, 2020). "The fluorescence intensity of EGFR in tumor cells was notably reduced by the treatment with RT, TNuF, or the combination." (PMID 32872195, 2020). "The tumor sections of subjects were immunohistochemically stained for basal markers, namely, 34βE12, c-Kit, and EGFR, in order to differentiate between BL and NBL subtypes." (PMID 32256581, 2020). "This indicated that local delivery of gemcitabine via a GEM implant inhibits tumor growth by suppressing EGFR signaling in xenograft tumors." (PMID 32111094, 2020). "Elevated expression of hnRNP A3 and EGFR was detected in the tumor section compared with the adjacent normal section." (PMID 32321917, 2020). "Patients with a higher level of PDL1 expression and high tumor mutational burden (TMB) have a higher response rate, and those with EGFR-/ALK- were better than those with EGFR+/ALK+." (PMID 32542150, 2020). "This mechanistic understanding will be key to unravel the functional consequences of anti-EGFR targeted therapies on the secretion of pro-tumoural EVs and their effects on drug resistance and microenvironment subversion." (PMID 33302515, 2020). "AREG, a tumor-derived exosome, can activate the epidermal growth factor receptor (EGFR) pathway in pre-osteoclasts to increase RANKL expression." (PMID 33195163, 2020). "In an experimental animal model, the pharmacological block of EGFR is correlated with aggravation of skin inflammatory conditions and increased production of chemokines in keratinocytes." (PMID 33375183, 2020). "The overexpression of EGFR that correlates with cancer cell proliferation, tumour growth, invasion and metastasis is common in human cancers including CRC." (PMID 33287803, 2020). "Epidermal growth factor (EGF) secreted by tumor cells and corresponding immune cells cooperates with up-regulated EGFR to accelerate this process." (PMID 33511267, 2020). "Rak’s laboratory previously reported a modulation of TF expression in tumor cells by EGFR activation and E-cadherin blockade." (PMID 32152404, 2020).
tumor (continued). "The results showed that although panitumab the degree of effective inhibition of EGFR signaling by mAb is similar to that of cetuximab, but it is less effective in mediating anti-tumor cell immune mechanisms." (PMID 32793499, 2020). "To enable therapeutic targeting of AAV to tumor cells, we computationally designed peptides intended to bind the dimerization arm region in domain II of EGFR." (PMID 33333826, 2020). "However, the category of TSA can be expanded to include tumour specific glycosylation, such as TnMUC1, tumour specific mutations in cell surface proteins, such as EGFRvIII and misfolded proteins that escape refolding within the endoplasmic reticulum, such as misfolded-EGFR." (PMID 31947597, 2020). "GC1118 exhibited anti-tumor efficacy comparable to that of cetuximab in a subset of PDXs, and EGFR amplification was a potential biomarker for predicting its therapeutic efficacy." (PMID 33142709, 2020). "These anti-tumour effects appear to be mediated by the downregulation of pKIT in the Golgi apparatus or EGFR in the endosomes." (PMID 31857719, 2020). "An OAd harboring a secreted anti-EGFR-scFv fused to the RNase onconase produced a potent EGFR-dependent bystander killing of tumor cells in vitro and enhanced tumor cell death in vivo." (PMID 32340119, 2020). "In the respective xenograft models only the combination of vandetanib plus irradiation reduced tumor growth more strongly than irradiation alone, and only in the EGFR expressing substrain." (PMID 32903756, 2020). "The LAMC2 has an epidermal growth factor (EGF)-like domain which can be processed by MMP to interrupt the hemidesmosomes via EGFR of b4 integrin during tumor cell migration." (PMID 32467737, 2020). "One arm of the BsAb recognizes the O-antigen of lipopolysaccharides (LPS) in the minicell membrane while the other targets a cancer-specific antigen such as epidermal growth factor receptor (EGFR) to support tumor-specific uptake." (PMID 32102476, 2020). "The transient combination of the IGF-1R inhibitor with continuous osimertinib eradicated the tumor cells and prevented the regrowth in CDX and PDX models of AXL-low-expressing EGFR-mutated NSCLC." (PMID 32929081, 2020). "Cisplatin treatment increased both IL-6 and IL-8 message levels in all sample types, especially in the EGFR mutant tumor samples." (PMID 32434541, 2020). "For example, the epidermal growth factor receptor (EGFR) activates Gli via its ability to stimulate the extracellular signal-regulated kinase pathway (ERK) during tumor development." (PMID 33228057, 2020). "With the gene ontology analysis, multiple genes involved in cell migration, adhesion and proliferation, as well as angiogenesis regulation, were significantly upregulated in tumours expressing EGFR and COL1A1." (PMID 32901137, 2020). "Currently, the reported reasons for EGFR-TKI acquired resistance are EGFR 20 exon T790M mutation, MET amplification, and phenotypic transformation of tumor cells." (PMID 33056982, 2020). "In this study, we found that EGFR is highly expressed in the tumour tissue of NPC patients with efficient metastases, as well as in highly metastatic NPC cell lines." (PMID 33304472, 2020). "An in vitro study showed that simultaneous inhibition of c-Met and EGFR pathways inhibits HCC tumor growth." (PMID 33195182, 2020). "Mechanistically, SAH-JGZ4 disturbed the in vivo interactions of EGFR–TRIB3 and EGFR–PKCα, and suppressed the expression of EGFR and PKCα in the inoculated tumor tissues." (PMID 32694521, 2020). "Studies have found that oncolytic adenovirus can exert anti-tumor effects through autophagic cell death induced by the E2F1-MIR-7 epidermal growth factor receptor (EGFR) pathway." (PMID 32069901, 2020). "In this latter case, we stratified patients who presented EGFR mutation or MET, ROS1 or ALK translocation, herein defined as mutated (Mut+), and compared them to the levels of tumor-associated caspase-4." (PMID 33187551, 2020).
tumor (continued). "We have translated a deeper knowledge of the signaling into new potential therapeutic strategies, suggesting that PI3Kβ is a good target for inhibition combined with EGFR inhibitor in this tumor type." (PMID 32672423, 2020). "One of the mechanisms for tumor cell-stimulated expression of PD-L1 is the activation of the EGFR, ERK1/2, PI3K-Akt, or Janus kinase 2/STAT1 signaling pathways." (PMID 32756527, 2020). "Our previous observations have shown significant differences in EGFR detection between tumor tissue samples extracted by various techniques in a retrospective analysis." (PMID 32640669, 2020). "GPER has been described as a tumor promoter in certain cancers such as breast cancer via activation of EGFR, STAT5 and MAPK/extracellular regulated kinase (ERK) pathways." (PMID 33363037, 2020). "In NSG mice models with the addition of an HLA-II mediated immunity, the combination of PCZ and Cetuximab in EGFR resistant tumors has a statistically significant tumor regression with durable response." (PMID 32516941, 2020). "EGFR inhibition also greatly instigated the anti-tumour effect of other BET inhibitors (iBET151 and iBET762)." (PMID 31937753, 2020). "Patients and Methods: Tumor (somatic) and blood (germline) DNA samples were obtained from two well-defined cohorts of mCRC patients, those sensitive and those resistant to EGFR blockade." (PMID 32796636, 2020). "Further investigation of molecular tumor markers, particularly EGFR, as a predictor of recurrence is required." (PMID 32523650, 2020). "A previous study used pharmacogenomics and molecular docking approaches to supplementary show epidermal growth factor receptor (EGFR)-transfected tumor cells were collaterally sensitive to honokiol compared with wild type cells." (PMID 32210117, 2020). "Studies have shown that important tumor-related factors, such as the epidermal growth factor receptor, sarbox-2, c-myc, and McL-1, are regulated by USPs." (PMID 32164618, 2020). "Cells derived from TNBC patients were used to perform tumor growth assays to further investigate the role of EGFR‐CAR NK cells in the inhibition of PDX tumor growth." (PMID 32592435, 2020). "In both studies, EGFR-expressing tumor cells were readily visualized in vivo, confirming the viability of antibody-conjugated fluorescent tumor identification in the presence of a BBTB." (PMID 32582530, 2020). "Pathological analysis, consisting of hematoxylin & eosin (H&E) and immunohistochemical (IHC) staining, was performed on tumor specimens from every animal to confirm tumor presence and EGFR status." (PMID 33042280, 2020). "In summary, the recombinant adenovirus Ad-SLPI-EGFRamiR-SLPI-revCASP3, armed with EGFR targeted artificial microRNA and recombinant caspase-3 under the control of tumor specific promoter SLPI, was successfully constructed." (PMID 32745124, 2020). "In recent years, it has been shown that tumour cells can transfer EGFR to other tumour cells and non-tumour cells using extracellular vesicles (EVs)." (PMID 33143170, 2020). "Despite the firmly-established significance of this pathway in tumor growth, however, targeted treatment aimed to disrupt EGFR has yielded only modest medical success in the past 2 decades." (PMID 32321917, 2020). "Overexpression of c-Src and EGFR occurs in many cancer cases, suggesting a close interaction between them and their potential contributions to tumor proliferation." (PMID 32296018, 2020). "Using 5-micron tumor sections of whole tumor xenografts, the authors performed ex vivo SERS mapping of entire tissue sections and provided near cellular-level spatial and temporal resolution of the PD-L1 and EGFR expression in tumor areas." (PMID 32545182, 2020). "We then used 15 patient-derived xenograft tumor samples to prove the possibility to obtain a correlation of an appropriately normalized expression level of EGFR with the response to Cetuximab." (PMID 31936310, 2020).
tumor (continued). "Cetuximab or other similar anti-EGFR antibody treatments alter Bcl-2 (anti-apoptosis) and Bax (pro-apoptosis) protein balance, promoting apoptosis in tumor cells; (g)." (PMID 32793499, 2020). "Several previous studies conducted similar longitudinal monitoring for T790M in NSCLC patients who had tumor progression on EGFR-TKI treatments." (PMID 33266057, 2020). "The anti-EGFR sdAb can also be fused to a tumor penetrating peptide to enhance its penetration into tumor tissue and increase its efficacy for cancer therapy." (PMID 33023595, 2020). "In brief, macrophages secrete epidermal growth factor (EGF), which interacts with its target receptor (EGFR) on the surfaces of tumor cells." (PMID 32182935, 2020). "β-catenin transactivation is critical for EGFR activation-enhanced glycolysis, tumor cell proliferation, migration, and invasion for tumor development." (PMID 32195176, 2020). "Active targeting, on the other hand, is mediated by the coupling of AuNPs with tumor-specific targeted drugs, such as EGFR monoclonal antibodies, to achieve AuNP active targeting of tumor cells." (PMID 33173417, 2020). "Tumor type (p = 0.46), expression of p-mTOR (p = 0.011), expression of EGFR (p = 0.046), and expression of PD-L1 (p = 0.023) had a significant impact on the targeted therapy recommendation rate." (PMID 33114048, 2020). "A large analysis, testing 1343 NSCLC tumor samples with NGS, showed a significant association between EGFR and PI3KCA or CTNNB1 mutations and between KRAS and STK11 mutations." (PMID 32365882, 2020). "A biomarker analysis showed a better PFS for patients with low-tumor PDGFR-alpha RNA in the combination arm, suggesting the relevance of tumor vascular microenvironment when combining angiogenesis and EGFR inhibitors." (PMID 36046069, 2020). "In contrast, inactivation of the EGFR pathway using tyrosine kinase inhibitors gefitinib and erlotinib or EGFR knockdown suppressed the proliferation of IBC cells through the MAPK/ERK pathway as well as tumor growth in vivo." (PMID 32883032, 2020). "Patients with advanced tumor grade and stage, and tumor relapse had significant increased expression of EGFR in comparison with patients with lower grade and stage of tumor, and lack of recurrence." (PMID 32795296, 2020). "This approach increased the tumor-to-liver ratio by ca. 7-fold for EGFR-targeting affibody molecules from 0.46 for [111In]In-DOTA-Z2377 (4 h pi) to 3.1 for [57Co]Co-DOTA-Z2377 (3 h pi) in an A431 xenograft model." (PMID 32075258, 2020). "The average lifespan of TNBC tumor‐bearing mice treated with EGFR‐CAR NK cells or si‐EGFR was longer than that of the mice treated with Con‐CAR NK cells." (PMID 32592435, 2020). "Mimecan is downregulated in several solid cancers and has a tumor-suppressive function through its interaction with epidermal growth factor receptor signaling and tumoral immune infiltration." (PMID 32887625, 2020). "The inhibition of EGFR in skin was related to a better median progression‐free survival, which explains the strong relationship between EGFR expression in skin and the tumor response." (PMID 33015988, 2020). "Another important observation was that the amount of tumor-specific EVs (enriched using tumor-specific markers anti-EGFR, anti-MAGEA3, anti-EpCAM, and anti-CSPG-4) varied among different patients." (PMID 33158181, 2020). "The IB data revealed that treatment with either Formo or osimertinib decreased the protein level of p-EGFR, p-Akt, and Mcl-1 in xenograft tumor tissues." (PMID 32276600, 2020). "The EGFR/PIK3 signalling pathway plays important roles in tumour progression, and these pathways are reported to be frequently altered in BC." (PMID 32445177, 2020).